MIR421 (microRNA 421)
Synonyms: hsa-mir-421; MIRN421
Gene: MicroRNA gene on chromosome X (74,218,377 to 74,218,461, reverse strand). Ensembl gene ENSG00000202566.
Gene Ontology:
Biological process: cellular response to amino acid stimulus; long-term synaptic potentiation; response to bacterium
Homologues: Orthologues: chimpanzee ptr-mir-421 (100% identical), pig ssc-mir-421 (100% identical).
Diseases named in the same sentence as MIR421 in open-access papers:
MIR421 is named in the same sentence as 2 diseases in open-access papers, as found by Europe PMC text mining. Sharing a sentence is not in itself a finding about the gene and the disease. The quoted sentences say what the papers report.
non-small cell lung carcinoma (1 paper, 2021). A group of at least three distinct histological types of lung cancer, including non-small cell squamous cell carcinoma, adenocarcinoma, and large cell carcinoma. "Furthermore, the overexpression of MIR421 has been previously shown to promote cancer cell proliferation in BC and in non-small cell lung cancer." (PMID 33436002, 2021).
cancer (2 papers, 2021 to 2023). A tumor composed of atypical neoplastic, often pleomorphic cells that invade other tissues. "In mass–type cancer, irregular shape cancer was associated with a sixfold downregulation of MIR421, compared with oval- or round-shape cancer." (PMID 37391754, 2023).